CD96 (CD96 molecule)
Diseases named in the same sentence as CD96 in open-access papers (continued):
Sharing a sentence is not in itself a finding about the gene and the disease.
tumor (continued). "TIGIT, DNAM-1, CD96, and CD112R are expressed on T cells and natural killer (NK) cells, while their respective ligands—CD155, CD112, CD113, and CD111—are expressed on APCs or tumor cells." (PMID 40356928, 2025). "CD96 originating from immune cells was found to enhance this effect through the CD155-CD96-Src-Stat3-Opa1 pathway, while inhibition of cancer cell CD96 enhanced chemotherapy response in BC tumor cells." (PMID 41421797, 2025). "In addition to its role as a prognostic marker, the overexpression of the PVR gene and its serum levels in MM points to its implication in immune evasion and tumor aggressiveness by interacting with immune checkpoint receptors such as TIGIT and CD96." (PMID 40369504, 2025). "CD96, CTLA - 4, and PDCD1 are key proteins in tumor immune evasion." (PMID 40746529, 2025). "Upon exploration of CD318 interactions with immune proteins, we found that CD96 and CD160 might be interacting with CD318 in COAD cancer, leading to the accumulation of CD8+ T Cells and CD56dim highly cytotoxic NK cells in the tumor microenvironment." (PMID 40725832, 2025). "CD96 belongs to the immunoglobulin superfamily and acts as a co-inhibitory receptor that competes with the co-stimulatory receptor CD226 for the shared ligands CD155 (PVR) and CD211 (NECTIN1), both of which are expressed on tumor and myeloid cells." (PMID 39811671, 2025). "TIGIT, DNAM1, and CD96 (TACTILE) are known receptors for PVR in the immune system; binding of PVR to TIGIT suppresses tumor immunity while binding to DNAM1 promotes tumor immunity; binding to CD96 acts both to suppress and promote tumor immunity." (PMID 39156900, 2024). "The addition of anti-CD96 in combination with anti-PD-1, anti-CTLA-4, anti-TIGIT, or doxorubicin chemotherapy resulted in superior antitumor responses by enhancing T-cell activity and suppressing tumor growth." (PMID 38732242, 2024). "CD96, a receptor protein that can regulate NK cell effector function and metastasis, is also of note as it can interact with CD155, and blocking CD96 can suppress primary tumor growth in mouse tumor models." (PMID 38732242, 2024). "Co-inhibition of PD-1 and CD96 improves CD8+ T-cell activity and reduces tumour growth." (PMID 38893071, 2024). "The modest but significant inhibition of T cell cytotoxicity supports earlier evidence that blocking CD96 in combination with other checkpoints promoted robust tumor control by murine CD8+ T cells, while blocking CD96 alone resulted in minimal tumor control by T cells." (PMID 36672244, 2023). "We found moderate positive correlation between the frequency of CD155 expression on mAPC populations and TIGIT and CD96 expression on T and NK cell subsets within the tumours, but not with CD226 or PD-1." (PMID 37596248, 2023). "Tissue samples with increased CD96 and PD1 expression might have an increased level of T cell exhaustion which could contribute to tumor progression." (PMID 37046787, 2023). "However, the exist of CD96 and TIGIT significantly inhibit the anti-tumor immune response of T cells." (PMID 37312116, 2023). "Studies have shown that IFN-γ production inversely correlates with the percentage of CD96+ NK cells in liver tissues and that reduced IFN-γ production could impair tumor immune responses." (PMID 36674817, 2023). "In this review, we will shed light on the brief discussion of the targeting strategy of NK-based checkpoint receptors especially CD96 and NKG2A receptors with monoclonal antibodies to exploit the potential anti-tumor activity of NK cells as a helper of T cell-based checkpoint immunotherapy." (PMID 36109471, 2023). "On the other hand, CD155 also binds checkpoint inhibitory receptors, including T cell immunoreceptor with Ig and ITIM domains (TIGIT) and T cell-activated increased late expression (Tactile or CD96), thus counteracting DNAM-1 action in the late phases of tumor progression." (PMID 37629138, 2023).
tumor (continued). "Together, our findings implicate a role for CD96 endodomain in attenuating T cell cytotoxicity and support combination tumor immunotherapy targeting multiple rather than single immune checkpoints." (PMID 36672244, 2023). "As a result, blocking both CD96 and PD-1 enhanced CD8+ TILs’ anti-tumor activity." (PMID 36674817, 2023). "Overexpression of immune checkpoint (CD96, PDL1, CTLA4) may lead to the depletion of anti-tumor immune cells in the microenvironment, which cannot play a good role in anti-tumor." (PMID 36744183, 2022). "Furthermore, GILncSig was found to be associated with the upregulation of the expression of immune checkpoints, such as CD274, CTLA4, CD96, and TIM-3, which induced tumor immunotherapy resistance." (PMID 35571034, 2022). "Even double knockouts of CD96 and PD-1 in wildtype and MC-38 tumor mice did not significantly compromise immune homeostasis." (PMID 36140247, 2022). "Dual blockade of CD96 with PD-1, PD-L1, TIGIT, or CTLA-4 increases antitumor response, and triple blockade of CD96, PD-1 and TIGIT yields the highest level of antitumoral immunity in various mouse tumor models." (PMID 35164813, 2022). "Early initiation of anti-PD-1 treatment in MC-38 mice resulted in a significant reduction in tumor growth compared to the control group, while anti-CD96 alone did not have any effect." (PMID 36140247, 2022). "Tumor immunity was reported to be promoted by the lack of host CD96 and PD-1, but immune homeostasis was not significantly injured." (PMID 36043142, 2022). "In addition, anti-CD96 therapy is effective in enhancing CD8+ T activity and limiting tumor growth and is more effective when administered in combination with blockade of a number of immune checkpoints, including PD-1, PD-L1, TIGIT, and CTLA-4." (PMID 34433460, 2021). "In addition, increased expression of the ligands for checkpoint inhibitors, such as PD1, CTLA4, TIM3, TIGIT, CD96, KLRG-1, and LAG3, on the tumor cells attenuates antitumor activity of NK cells." (PMID 34768814, 2021). "Blocking the CD96−CD155 interaction restores NK cell immunity to tumor by reversing NK cell depletion or TGF-β1 reversing NK cell depletion, suggesting that CD96 may have a therapeutic role in HCC." (PMID 34869376, 2021). "Combining blockade of the inhibitory receptor CD96 or administration of low-dose IL-15 with CIS inhibition could further boost NK cell activity and enhance protection against tumor metastasis." (PMID 33946954, 2021). "However, during tumor progression liver resident NK cells in tumor tissue down regulate NKG2D and express inhibitory receptors PD-1, CD96, and TIGIT and are rapidly exhausted." (PMID 34071188, 2021). "In addition to HLA-specific inhibitory and activating NK receptors—Killer-cell immunoglobulin-like receptors (KIRs), NK cells express inhibitory receptors including PD-1, TIGIT, CD96, TIM-3 and CD161 for anti-tumor activity." (PMID 34572387, 2021). "To clarify the specific cell types modulated by CD96 in tumor microenvironment (TME), we explored the correlations between CD96 expression and immune infiltrating levels in LGG and SKCM based on sets of immunological markers using the TIMER2.0 database, with ACC serving as a control cohort." (PMID 33680972, 2021). "Blockade of CD96 and PD1-PDL1 was able to improve tumor control." (PMID 34691288, 2021). "Additionally, we found potentially attractive targets in CD96 and CD18 (ITGB2), each of which has demonstrated some significant impact on anti-tumor immunity in pre-clinical studies with the potential for translation in the future." (PMID 32059711, 2020). "In particular, CD155 once up-regulated on different types of tumor cells is recognized by a group of receptors expressed on T and NK cells: The activating receptor DNAM-1 (CD226) and the inhibitory receptors TIGIT and TACTILE (CD96)." (PMID 32019260, 2020).
tumor (continued). "Therefore, TIGIT, CD96, and CD155 are deemed as key immune checkpoints for NK cells, and the blockade of these molecules has shown great promise in tumor immunotherapy." (PMID 32714324, 2020). "While TIGIT targeting on NK cells, either alone or in combination with other ICs, leads to the restoration of anti-tumor activities, the functional consequence of TIGIT and/or CD96 blockade on ILCs remains unknown." (PMID 33255582, 2020). "Patients with a higher cumulative percentage of CD96+ NK cells within tumours also exhibit poorer disease-free survival, suggesting that TGF-β1 regulates the cytotoxic potential and cell immunity of NK cells against tumour cells." (PMID 33114183, 2020). "However, it is important also to consider that tumor progression facilitates the expression of the inhibitory receptors TIGIT and CD96 that compete with DNAM-1 for CD155 binding and dampen cytotoxic response." (PMID 32019260, 2020). "Inhibition of some NK cell surface checkpoint receptors has displayed the potential to reverse NK cell dysfunction in tumors, and to boost anti-tumor immunity, both in clinical trials (anti-KIR and anti-NKG2A), and in preclinical studies (e.g., anti-TIGIT, and anti-CD96)." (PMID 31552017, 2019). "Furthermore, we observed that platelet cloaked tumour cells have significantly decreased expression of the CD112 and CD155 ligands that activate CD226/CD96." (PMID 30908480, 2019). "A similar effect was observed for CD96 with significantly decreased expression in response to platelet cloaked tumour cells, platelets and releasate suggesting a role for both in CD96 suppression, suggesting that CD226 and its CD96 co-receptor are suppressed in concert." (PMID 30908480, 2019). "Despite efficacy in certain preclinical tumor models, whether blockade of TIGIT and/or CD96 modulates NK cell effector function and results in clinical responses in human cancer patients remains to be seen." (PMID 30250471, 2018). "We observed that the expression of genes involved in NK crosstalk with DCs and tumour cells (DNAM1, CRTAM, CD96), promoting NK cell activation (NCR3(NKp30)) or modulating NKT activity (CD1d) was strongly and positively correlated with that of the 5 previously identified markers of good prognosis." (PMID 23758773, 2013). "At present, tumor-related immunomodulators have become an important method for BC treatment, and in this study, we found that DHCR7 expression is significantly correlated with the immunoinhibitor, immunostimulators, and MHC molecules, including CD96, CD48, and HLA-DPB1." (PMID 38526324, 2024). "Furthermore, we established tumor‐bearing mouse models and proved that anti‐TIGIT, anti‐CD96, and anti‐PD1 could remarkably inhibit the growth of CC cells in vivo; yet no statistical differences were found between these three groups." (PMID 36725337, 2023). "T cells with a chimeric receptor displaying the extracellular domain of HER2 and the intracellular domain of CD96 showed decreased killing activity against HER2-positive tumor cells compared to T cells lacking the intracellular CD96 domain in vitro and in vivo." (PMID 37046787, 2023). "However, the presence of NK cells is typically reduced in established tumors because of the elevated expression of inhibitory receptors, such as TIGIT, CD96, and TIM3, on tumor-infiltrating NK cells, leading to a substantial impairment of their anti-tumor functionality." (PMID 37876793, 2023). "Interestingly, the combination of CD96‐blocking antibody and docetaxel significantly reduced tumor growth in models with MCF‐7 BCSCs expressing high levels of CD96, with limited tumor growth in MCF‐7 cells expressing low levels of CD96." (PMID 36581470, 2023). "Both TIGIT and CD96 inhibit NK and T cell function via binding to CD226, indicating a possibility that ITGAL may suppress NK and CD8+ T cell’s killing activities of tumor cells." (PMID 37835514, 2023).
tumor (continued). "Furthermore, unlike CD226, CD96 was dispensable for killing of CD155-expressing tumor cells, suggesting that the stimulatory effect of CD226 is dominant." (PMID 35998045, 2022). "However, considering the low protein expression of CD96, we do not recommend utilizing it as a molecular biomarker for tumor diagnosis." (PMID 33680972, 2021). "It has been speculated that CD155 expression leads to tumor immunosuppression, because the interaction of CD155 with TIGIT or CD96-positive T lymphocytes and NK cells results in exhaustion of immune function, in addition to reducing the secretion of interferon-γ." (PMID 34115802, 2021). "Currently, the physiological roles in tumor surveillance by NK cells, as well as the therapeutic potential, of many surface receptors on NK cells have been demonstrated (e.g., KIR, TIGIT, NKG2A, CD96, and PD-1), while those of many others still remain to be shown (e.g., LAG-3 and TIM-3)." (PMID 31552017, 2019). "The discovery of CD96 upregulation in T cells and NK cells within human tumors led to the the hypothesis that the inhibition of the CD155/CD96 could essentially influence the tumor elimination." (PMID 28073373, 2017). "Interestingly, the original phage display library demonstrated only very weak binding activity to CD96-positive tumor cells, indicating that an excess of non-functional scFvs were present in the original library." (PMID 22879978, 2012). "Notwithstanding the lack of a mechanistic investigation of how CD96 inhibited cytokine production and tumor killing by NK cells, these findings, together with those described for mouse NK cells, suggest that CD96 negatively regulates the anti-tumor responses of mouse and human NK cells." (PMID 36672244, 2023). "Overexpression of nectin-1 in tumor cells is not described, but nectin-1 serves as an entry receptor for herpesviruses in human and mouse and therefore control of infection via CD96 expressed by NK cells may differ between species." (PMID 29868026, 2018). "Most published data demonstrate the role of CD96 in tumor cell metastasis mediated by NK cells rather than CD8+ T cells, necessitating research into CD96 regulation of CD8+ T cells." (PMID 36674817, 2023). "Tumor exposure alone or with TIGIT blockade did not change the frequency of NK cells expressing inhibitory receptors TIM-3, NKG2A, LAG-3, PD-1, or CD96 compared to isotype control or unexposed NK cells." (PMID 37345049, 2023). "Their study showed that CD96 competes with CD226 for CD155 binding and negatively regulates IFN-γ secretion in NK cells; however, it does not affect the direct killing of tumor cells by NK cells." (PMID 31681269, 2019). "The regulation of CD96 on the NK cell is, unlike CD226, independent of the suppressive effects of the tumour cell alone." (PMID 30908480, 2019). "Neutralising CD96 on the NK cell, or the ligands CD155 or CD112 on the tumour cell, did not disrupt NK cell targeted killing of our tumour cell lines." (PMID 30908480, 2019). "Recent evidence indicates that CD96, which binds CD155 but not CD112, negatively regulates tumor immunity and cytokine secretion by NK cells." (PMID 25384044, 2014). "Conversely, TBRG4 showed a negative correlation with CD96 and TNFSF15 (P < 0.05, R < −0.1), suggesting it may influence pathways that inhibit T cell function, thereby fostering a more immunosuppressive tumor microenvironment." (PMID 40260662, 2025).
cancer (89 papers, 2016 to 2025). A tumor composed of atypical neoplastic, often pleomorphic cells that invade other tissues. "In summary, our findings demonstrate that CD96 is highly expressed in various cancer cell subsets and is associated with malignancy in BC." (PMID 36581470, 2023). "COSMIC provided detailed information on the CD96 mutation types, including substitution missense, non-sense, and synonymous mutations in different cancers." (PMID 33680972, 2021). "CD96 plays significant but contradictory roles in different cancers: it’s a distinctive risk and protective factor for LGG and SKCM, respectively." (PMID 33680972, 2021). "CD96 has been the subject of investigation as an additional target of immune checkpoint inhibition in cancer immunotherapy." (PMID 39811671, 2025). "We observed a transition from CD8+ T cells expressing CD226 and CD96 to those expressing TIGIT once these cells had infiltrated into the cancer nest, consequently disrupting the immune equilibrium between the three receptors observed in healthy lungs." (PMID 38279870, 2024). "Other receptors, such as CTLA-4, TIM-3, TIGIT, and CD96, should be studied more thoroughly for their potential clinical targeting for cancer immunotherapies." (PMID 39339180, 2024). "For instance, in the Oncomine database, CD96 mRNA expression was found to be higher in cancer tissues from brain, breast, kidney, and leukemia than in paracancerous tissues." (PMID 36674817, 2023). "Accordingly, CD226 agonism in combination with appropriate antagonistic anti-TIGIT and/or anti-CD96 antibodies represents an attractive therapeutic strategy in the context of cancer immunotherapy." (PMID 36944702, 2023). "CD96 mRNA expression in human tissue samples of different cancer types showed a high correlation with T-cell markers and also with the PD1 checkpoint receptor." (PMID 37046787, 2023). "On the contrary, CD96 mRNA levels were lower in cancers of lung, rectal, and thyroid compared to normal tissue." (PMID 36674817, 2023). "CD96 participates in a variety of immune responses, controls immune cell infiltration, and affects the malignant characteristics of various cancer types, so it is a potential biomarker to determine patient prognosis and immune infiltration." (PMID 36918563, 2023). "This distribution of CD96 genes in cancer tissues showed low cancer specificity, and all cancer tissues had very low levels of CD96 gene expression, with the stroma of cancerous tissues expressing moderately." (PMID 36674817, 2023). "Next, to study the correlation between CD96 and pan-cancer infiltration of various immune cells, the IMER 2.0 database was used." (PMID 36674817, 2023). "At the same time, the abundance of CD96 positively correlates with the infiltration level of immune cells in many cancers." (PMID 36674817, 2023). "In this mini-review, we aim to discuss the basic biology of CD96 as well as the most recent relevant research on this as a promising candidate for cancer immunotherapy." (PMID 36674817, 2023). "All together, these results highlight the importance of the CD155/TIGIT/CD96/DNAM-1 axis in cancer immune surveillance outcome." (PMID 37629138, 2023). "Additional research is needed to further elucidate the exact function of the CD96 immune checkpoint pathway in human cancer." (PMID 37046787, 2023). "There are contradictory study results regarding the good or poor prognostic influence of high CD96 expression in different human cancer types." (PMID 35406584, 2022). "CD96 can promote cancer metastasis by enhancing NK cell-target adhesion and inhibiting the NK-mediated cytokine response." (PMID 35433683, 2022). "In the study, we found that CD96 was upregulated in various types of cancers from the data in TCGA and GTEx dataset." (PMID 36043142, 2022). "Platelet cloaking actively disrupts the CD226/CD96–Nectin-2/Necl-5 axis of circulating cancer cells recognition and plays a significant role in metastatic cascade." (PMID 36553083, 2022).